LGALS1 (galectin 1)
Diseases named in the same sentence as LGALS1 in open-access papers (continued):
Sharing a sentence is not in itself a finding about the gene and the disease.
infection (continued). "Galectin-1 may be concentrated in the vicinity of this virological synapse and more favourably act upon infection." (PMID 19032754, 2008). "Furthermore, soluble galectin-1 increases HTLV-I cellular infection by HTLV-I gp46-pseudotyped HIV-1 virions." (PMID 19032754, 2008). "Moreover, an updated study demonstrated that galectin-1 was an inflammatory damage-associated molecular pattern (DAMP) whose release was elicited by cytosolic lipopolysaccharide (LPS) sensing during Infections caused by Gram-negative bacteria." (PMID 37047471, 2023). "However, during infection of the Dengue virus, galectin-1 seems to perform an anti-infection role." (PMID 37047471, 2023). "Thus, the pro-infection abilities of galectin-1 are twofold." (PMID 37047471, 2023). "Galectin-1 formed rare puncta but did not associate with R. equi.Our detection of a galectin-positive population of R. equi suggests that phagosomal membrane damage and access to the cytosol occurs as early as 4h following infection." (PMID 34473814, 2021). "Prior clinical studies have shown higher levels of IL-1β and IL-8 in women with concurrent BV and TV as compared to women with neither infection; however, we show for the first time higher levels of galectin-1, RANTES, and IP-10 to be associated with incident TV in women with BV only." (PMID 34422675, 2021). "Furthermore, changes in galectin-1 expression by various immune cells were most prominent in the liver during the first 14 days of infection, which may have contributed to the tissue-specific impact on parasite control we observed." (PMID 29075269, 2017). "In this study, we demonstrated that genetic variants of LGALS1, including rs4820294 and rs13057866 and the related variants, encode the higher expression of LGALS1 in humans, which may confer the carriers of these variants more protection from A(H7N9) infection." (PMID 25687228, 2015). "Beyond CXCL5, our machine-learning approach highlighted several other novel candidates: PDGF-B, Galectin-1, CXCL11, ANGPT1, EGF, TIE2, MCP-2, and NOS3 that each outperformed CXCL5 in discriminating a dormant infection from uninfected joint replacements." (PMID 41387890, 2025). "This analysis identified a signature for 4 genes, CEBPD (0.93 log2FC), MAFB (0.83 log2FC), IFITM3 (0.55 log2FC), and LGALS1 (−0.53 log2FC), that was markedly enriched in CD14 monocytes in patients who ultimately survived infection." (PMID 35169146, 2022). "To further investigate the biological role of Gal-1 in H-1PV infection, we took advantage of the CRISPR-Cas9 technology and established the NCH125 LGALS1 knockout cell line (LGALS1 KO)." (PMID 35632759, 2022). "Seven infection/inflammation-related proteins in our assay, S100A9, VIM, LGALS1, APCS, MMP9, LDHA, and CRP, were elevated in TB-PEs and the other-infectious-PEs." (PMID 35197508, 2022). "It was ascertained that galectin-3 and -8, as well as galectin-1 and -7, colocalized with GAS-surrounding Tollip at 4 h post-infection." (PMID 33425778, 2020). "Our RNA-seq data showed upregulation of two members of the galectin family, i.e., galectin-3 (up ∼140-fold) and galectin-1 (up ∼87-fold), in activated TN CD8+ T cells during the acute phase of infection with MHV68." (PMID 30388704, 2018). "As described for HIV, galectin-1 was found to stabilize attachment of HTLV-1 to human T cells, resulting in increased efficiency of infection as well as increased fusion of HTLV-1 infected cells." (PMID 24995007, 2014). "In our search for new antiviral compounds to combat infection by dengue virus type 1 (DENV-1), we investigated the role of galectin-1, a widely-expressed mammalian lectin with functions in cell-pathogen interactions and immunoregulatory properties." (PMID 25392933, 2014). "Alterations were noted in the expressions of galectin-1, -3, -3BP, -9, -12, and -13; the majority of galectins increased regardless of infection type." (PMID 36977257, 2023).
infection (continued). "Worthy of note is that while “knocking out” galectin-1 and blocking galectin-1 with antibodies reduce the attachment of ZIKV to human A549 cells by about 40 to 60%, silencing of galectin-1 in MNCs reduces the attachment and infection of ZIKV by close to 80%." (PMID 36404916, 2022). "To test whether galectins were recruited to Mtb phagosomes early after infection, we generated 3×FLAG (FL)-tagged expression constructs of four different galectins: galectin-1, -3, -8, and -9." (PMID 34225486, 2021). "Furthermore, galectin-1 knockout resulted in a significant rise in the proliferation rate of intracellular GAS at 4 and 6 h post-infection." (PMID 33425778, 2020). "First, we stimulated cervical epithelial cells with escalating doses of recombinant galectin-1 or -3 in the presence or absence of Trichomonas (B7RC2) infection and measured galectin levels in 24-h cell culture supernatants." (PMID 26589797, 2016). "Galectin-1 expression on monocytes did not change in the liver and decreased in the spleen, but due to increased leukocyte numbers in these tissues as a result of infection, the number of monocytes expressing galectin-1 was increased in both tissues." (PMID 29075269, 2017). "It is not clear why galectin-1 is expressed on multiple immune cell populations in the liver during L. donovani infection, and only influences parasite control in this tissue at the acute stage of infection." (PMID 29075269, 2017). "The results of our galectin-1 immunohistochemistry and urine inhibition assay support the hypothesis that the toxic effect of urine in the prepuce prevents the establishment of infection with T. foetus in calves, rather than a lack of host cell receptor expression in prepubescent animals." (PMID 40431243, 2025). "Thus, we hypothesize that IGHG1 and LGALS1, detected early in E. granulosus infection, induce EMT initiation in the host liver cells; this results in vimentin expression in the middle infection stage, followed by persistent increases in expression in the late infection stage." (PMID 39625960, 2024).
metabolic disease (7 papers, 2021 to 2026). A congenital disorder (due to inherited enzyme abnormality) or acquired (due to failure of a metabolically important organ) disorder resulting from an abnormal metabolic process. "We thoroughly characterized the association patterns of galectin-1 and galectin-3 to established and exploratory markers of metabolic disease in a community-based cohort." (PMID 38777863, 2024). "Galectin-1 is newly emerging as a potential biomarker associated with metabolic diseases." (PMID 41590667, 2026). "Experimental studies indicate a role for galectin-1 and galectin-3 in metabolic disease, but clinical evidence from larger populations is limited." (PMID 38777863, 2024). "Based on the current knowledge, galectin-1, 2, 3, 9 and 12 are involved in metabolic disorders, and gal-3 and 9 have been fairly exhaustively studied." (PMID 37892153, 2023). "Recently, several galectins, including galectin-1, have also been identified as important for adipose tissue homeostasis, both as regulators of adipose tissue function, and in metabolic disease." (PMID 36295832, 2022). "It is also suggested that targeting galectin-1 may represent a new way to treat a wide spectrum of metabolic diseases by modulating PPARγ activity." (PMID 33431823, 2021). "Association between LGALS1 (gal-1 gene) and GDM complicated pregnancy, LGALS2 (gal-2 gene) and fasting insulin and glucose has been reported, however, further studies are necessary to understand their roles in the development of metabolic disorder during gestation." (PMID 35046934, 2021).
adenocarcinoma (4 papers, 2020 to 2025). A common cancer characterized by the presence of malignant glandular cells. "We found that shed SDC-1 and MMP-7 levels were significantly lower, whereas Mesothelin and Galectin-1 levels were significantly higher in malignant mesothelioma effusions, compared to adenocarcinoma." (PMID 32731396, 2020).
cardiovascular diseases (4 papers, 2020 to 2025). "The search strategy incorporated relevant keywords, such as “Galectin-1”, “cardiovascular diseases”, “inflammation”, and “biomarkers”, to identify studies with mechanistic insights and clinical relevance." (PMID 40572708, 2025). "Galectin-1 (Gal-1), a β-galactoside-binding lectin, plays a complex role in cardiovascular diseases (CVDs), exerting both protective and pathological effects depending on the context." (PMID 40572708, 2025). "Our findings corroborate the literature regarding the important roles of galectin-1, galectin-9, and alpha-1-microglobulin in cardiovascular diseases." (PMID 39767748, 2024). "Immunomodulatory proteins have been demonstrated to play a role in the development and progression of cardiovascular diseases, including galectin-1, galectin-9, and alpha-1-microglobulin." (PMID 39767748, 2024). "As galectin-1 can modulate the inflammatory response in cardiomyocytes, galectin-dependent signaling is an attractive target for the diagnosis and treatment of cardiovascular disease." (PMID 33244142, 2020). "Taken together, these findings explain the biological mechanisms through which galectin-1, galectin-9, and alpha-1-microglobulin are related to cardiovascular disease progression, and therefore, may act as prognostic biomarkers for MACE in patients with PAD." (PMID 39767748, 2024). "Compared with systemic inflammation, galectin-1 elevation may proceed via a different mechanism in myocardial injury, making it more specific to cardiovascular disease." (PMID 33244142, 2020).
retinopathy (4 papers, 2017 to 2023). "The RNA-binding protein galectin-1 (Gal-1) participates in pathological RNV in oxygen-induced retinopathy mouse models." (PMID 37322431, 2023). "In a study of oxygen-induced retinopathy of mice, galectin-1 levels were increased, and immunostaining indicated increased galectin-1 expression close to retinal neovessels." (PMID 36295832, 2022). "Another study of oxygen-induced retinopathy in mice examined the effect of galectin-1 silencing through intravitreal adenoviral interference injection and discovered that while retinal neovascularization was reduced, there was no negative effect on normal vessel growth or vessel perfusion." (PMID 36295832, 2022). "As retinal impairment involves abnormal neovascularization and neuronal degeneration, we evaluated here the involvement of galectin-1 in vascular and non-vascular alterations associated with retinopathies, using the oxygen-induced retinopathy (OIR) model." (PMID 28455954, 2017). "Furthermore, intravitreal injection of the galectin-1 inhibitor OTX008 significantly reduced the number of preretinal neovascular cells and the retinal neovascularization area, which were otherwise increased in the oxygen-induced retinopathy model." (PMID 36295832, 2022).
bacterial infection (3 papers, 2016 to 2023). "Overall, on the one hand, galectin-1 facilitates bacterial infection via diminishing the host immune response, protecting bacterial causative proteins as well as mediating the transport of bacteria." (PMID 37047471, 2023). "Herein, we found that galectin-1 and -7 also play a critical role in the intracellular immune response against bacterial infection." (PMID 33425778, 2020). "The highest level of galectin-1, galectin-3, and E-selectin was detected in the bacterial infection group." (PMID 27240351, 2016). "We determined that Tollip participates in bacterial autophagy in response to bacterial infection by regulating the recruitment of other autophagy receptors and galectins, and we further demonstrated that galectin-1 and -7 play a crucial role in the defense against bacterial infection." (PMID 33425778, 2020). "Bacterial infection induced the highest level of galectin-1 among all groups." (PMID 27240351, 2016). "Taken together, these results signified that galectin-1 and -7 respond to GAS infection and function in bacterial autophagy to defend against bacterial infection." (PMID 33425778, 2020). "Of note, the anti-inflammatory effects of galectin-1 do not always play the role of “evildoer” in bacterial infection." (PMID 37047471, 2023).
immune disorders (3 papers, 2022 to 2024). "Accumulating evidence demonstrates that galectin-1 and its ligands are important regulators of immune responses such as T-cell homeostasis and survival, T-cell immune disorders, and chronic inflammation." (PMID 39767748, 2024).
kidney disease (3 papers, 2021 to 2022). "In recent years, several studies have examined the potential use of circulating galectin-1 as a potential biomarker in T2D and predictor of adverse events and explored its possible role in modulating kidney disease." (PMID 36295832, 2022). "Earlier studies have proposed a role for galectin-1 in kidney disease but were mainly based on smaller experimental studies." (PMID 34743218, 2022). "Of the remaining proteins, which have rarely been reported with regard to their function in renal disease, we conducted validation experiments on two proteins, protein S and galectin-1, to confirm their potential status as candidates in renal pathogenesis." (PMID 33453410, 2021). "Together, these studies demonstrate increased levels of galectin-1 during the progression of kidney disease, but do not provide insight as to the specific role of galectin-1 in this process." (PMID 36295832, 2022).
neurodegenerative disease (3 papers, 2021 to 2022). A disorder of the central nervous system characterized by gradual and progressive loss of neural tissue and neurologic function. "In neurodegenerative diseases, galectin-1,-8, and -9 have neuroprotective and anti-inflammatory activities." (PMID 34720894, 2021). "These consisted of markers of astrocytic and microglial activation (GFAP, vimentin, galectin-1, and clusterin) and indicators of neurodegenerative disease (ApoE and serpinA3N) that each demonstrated significant prion effects and PAM effects from the MS proteomic analysis." (PMID 36378750, 2022).
infectious disease (2 papers, 2017 to 2025). A disorder directly resulting from the presence and activity of a microbial, viral, or parasitic agent in humans. "Together, these findings provide new insights into the role of galectin-1 in modulating immunity during infectious diseases and highlight both tissue- and disease-specific roles for this molecule." (PMID 29075269, 2017).
inflammation (2 papers, 2021 to 2024). Aberrant reaction of the microcirculation characterized by movement of fluid and leukocytes from the blood into extravascular tissues. "Given that systemic atherosclerosis is primarily a disease of chronic inflammation, these mechanisms may explain the important role of galectin-1 in PAD, CAD, and CVD." (PMID 39767748, 2024). "Although the precise mechanisms by which mature Tregs utilize galectin-1 during DSS inflammatory challenge are unclear, these data highlight the importance of endogenous galectin-1 as a novel determinant in regulating T cell reactivity during the development of intestinal inflammation." (PMID 34262567, 2021).
LGALS1 also shares sentences with these, for which no sentence is quoted: clear cell renal cell carcinoma (5 papers); multiple myeloma (5); chronic lymphocytic leukemia (3); fetal growth restriction (3); Hyperinsulinemia (3); macrosomia (3); nasal polyps (3); acute lymphoblastic leukemia (2); adenoma (2); celiac disease (2); colorectal tumors (2); diabetic macular edema (2); diffuse large B-cell lymphoma (2); fibrosis (2); gastritis (2); gingivitis (2); graft versus host disease (2); papillary carcinoma (2); psoriasis (2); systemic sclerosis (2); thyroid tumor (2); trophoblastic tumor (2); acute lung injury (1); acute promyelocytic leukemia (1); age (1); allergic asthma (1); amyotrophic lateral sclerosis (1); angina (1); B-cell precursor acute lymphoblastic leukemia (1); benign ovarian tumours (1).
A further 79 diseases each share a sentence with LGALS1 in 1 paper.